CHCHD5 (coiled-coil-helix-coiled-coil-helix domain containing 5)
Synonyms: C2orf9; MGC11104; MIC14; MIX14; CHTM1
Tractability: PROTAC: ubiquitination databases record sites on it.
Gene: Protein-coding gene on chromosome 2 (112,584,240 to 112,589,275, forward strand). Ensembl gene ENSG00000125611.
Subcellular location: Mitochondrion intermembrane space
Subcellular location (Human Protein Atlas): Mitochondria
Pathways (Reactome):
Protein localization: Mitochondrial protein import
Gene Ontology:
Molecular function: protein binding
Biological process: cellular respiration
Cellular component: mitochondrion; mitochondrial intermembrane space
Genetic constraint (gnomAD): Loss-of-function variants: 11 observed, 17.93 expected, observed/expected ratio (o/e) 0.61, 90% interval 0.38 to 1.01. The upper end of that interval is the gene's LOEUF score, 1.01, which puts it in group 4 of 6, group 1 being the genes least tolerant of losing a copy. Missense variants: 163 observed, 158.67 expected, observed/expected ratio (o/e) 1.03, 90% interval 0.9 to 1.17. Synonymous variants: 55 observed, 59.19 expected, observed/expected ratio (o/e) 0.93, 90% interval 0.75 to 1.16.
Homologues: Orthologues: macaque CHCHD5 (96% identical), chimpanzee CHCHD5 (95% identical), rat Chchd5 (90% identical), dog CHCHD5 (88% identical), mouse Chchd5 (88% identical), pig CHCHD5 (88% identical), rabbit CHCHD5 (85% identical), guinea pig CHCHD5 (85% identical), tropical clawed frog chchd5 (52% identical). Paralogues in human: COX19 (14% identical).
Diseases named in the same sentence as CHCHD5 in open-access papers:
CHCHD5 is named in the same sentence as 14 diseases in open-access papers, as found by Europe PMC text mining. Sharing a sentence is not in itself a finding about the gene and the disease. The quoted sentences say what the papers report.
Obesity (2 papers, 2021). Accumulation of substantial excess body fat. "Recently, CHCHD5 has been reported to be associated with hypertension and obesity in a Chinese population." (PMID 34670603, 2021).
CHCHD5 also shares sentences with these, for which no sentence is quoted: amyotrophic lateral sclerosis (2 papers); frontotemporal dementia (2); adenocarcinoma (1); breast carcinoma (1); cancer (1); colon cancers (1); colon tumors (1); hepatocellular carcinoma (1); Hypertension (1); large cell carcinoma (1); lung carcinoma (1); squamous cell carcinoma (1); tumor (1).